CDKN2A (cyclin dependent kinase inhibitor 2A)
Diseases named in the same sentence as CDKN2A in open-access papers (continued):
Sharing a sentence is not in itself a finding about the gene and the disease.
pancreatic ductal adenocarcinoma (46 papers, 2005 to 2026). An infiltrating adenocarcinoma that arises from the epithelial cells of the pancreas. "Specifically, in carriers of a germline pathogenic variant in CDKN2A, the risk of pancreatic ductal adenocarcinoma seems to be higher than previously reported." (PMID 36980574, 2023). "Pathogenic germline CDKN2A variants are associated with an increased risk of pancreatic ductal adenocarcinoma (PDAC)." (PMID 35001868, 2022). "It is reported that approximately 60% of patients with pancreatic ductal adenocarcinoma carry the CDKN2A mutation, and this mutation is associated with a high risk of tumor development." (PMID 34616403, 2021). "The mutation of cyclin dependent kinase inhibitor 2A (CDKN2A) is frequently found in pancreatic ductal adenocarcinoma (PDAC)." (PMID 33322698, 2020). "Indeed, approximately 95% of pancreatic ductal adenocarcinomas have functional loss of the CDKN2A gene." (PMID 39420514, 2025). "Moreover, it is known that CDKN2A mutation occurs in early PDAC (pancreatic ductal adenocarcinoma) and, CDKN2A promoter hypermethylation is related to malignant tumor development." (PMID 34439790, 2021). "The p16INK4A/CDKN2A is known to be a tumor suppressor gene located at chromosome 9p that is inactivated in most pancreatic ductal carcinomas in humans (80–95%) by intragenic mutations (40%), homozygous deletions (40%) or hypermethylation of its promoter region (15%)." (PMID 24212630, 2011). "In patients with pancreatic ductal adenocarcinoma (PDAC), germline CDKN2A VUSs affecting p16INK4a, most often rare missense variants, are found in up to 4.3% of patients." (PMID 38234851, 2025). "Recent studies have shown that MIR31HG‐TAD is adjacent to CDKN2A‐TAD in various pancreatic ductal carcinoma cell lines." (PMID 37426677, 2023). "Three percent of patients with pancreatic ductal adenocarcinoma (PDAC) present a germline pathogenic variant (GPV) associated with an increased risk of this tumor, CDKN2A being one of the genes associated with the highest risk." (PMID 36980574, 2023). "Germinal mutations in BRCA2, p16/CDKN2A, STK11, and PRSS1 have been associated with an increased risk of pancreatic ductal carcinoma." (PMID 32498335, 2020).
pancreatic ductal adenocarcinoma (continued). "Such genetic events on the CDKN2A gene may play an important role possibly at a later step in the progression of pancreatic ductal carcinoma." (PMID 35004697, 2021). "Such genetic events in the CDKN2A gene may play an important role in pancreatic ductal carcinoma." (PMID 35004697, 2021).
chordoma (41 papers, 2008 to 2025). Chordomas are rare malignant tumors arising from embryonic remnants of the notochord in axial skeleton. "Previous data showed that palbociclib reduced cell viability and proliferation in CDKN2A-deficient chordoma cell lines." (PMID 40627883, 2025). "Deficiencies of PTEN and CDKN2A are two of the most frequent molecular alterations found in chordoma cases, often being associated with a poor prognosis." (PMID 39407739, 2024). "Other key mutations of dedifferentiated chordoma from the meta-analysis include CDKN2A/B, IRF2, KIT, PIK3CA, PTEN, RB1, and the TERT promoter." (PMID 38892063, 2024). "Loss of PTEN and CDKN2A (encoding p16) is one of the most common molecular changes seen in chordomas; poor prognoses are linked to particular inhibitors of the PI3K/AKT/mTOR pathway and CDK4/6." (PMID 39233954, 2024). "Genetically, chordomas are notable for the loss of CDKN2A and PTEN expression and large copy number losses, particularly in chromosomes 1p, 3, 9, 10, 13, 14, and 18; copy number gains are rare." (PMID 38892063, 2024). "As one of the most prevalent genetic alterations in chordoma, homo- (11.25–30% in chordoma) or heterozygous loss of chromosome 9p21 (about 70% in chordoma) with loci of cyclin-dependent kinase inhibitor 2A/2B (CDKN2A/2B), has been described in several cohorts." (PMID 38369555, 2024). "Previous studies had observed genetic and protein loss of CDKN2A-p16 in different chordoma cohorts, and we also detected a heterozygous deletion that involved the depletion of CDKN2A/2B/2C and gain of CCND2 and CDK6." (PMID 38369555, 2024). "The most frequent molecular alterations include the loss of PTEN and CDKN2A (encoding p16), being associated with poor prognoses in chordoma patients." (PMID 37046638, 2023). "For example, U-CH2 and MUG-Chor1 chordoma cell lines each show biallelic loss of CDKN2A, as well as highly selective dependence on CDK6." (PMID 37024492, 2023). "Palbociclib, a specific inhibitor of CDK4/6, has recently been tested in in vitro cell line chordoma models harboring the loss of CDKN2A and showed an efficient inhibition of the tumor cell growth." (PMID 36505864, 2022). "For example, palbociclib is an approved CDK4/6 inhibitor for chordomas with CDKN2A gene loss and is currently being evaluated in a clinical trial (NCT03110744)." (PMID 36248987, 2022). "From our chordoma xenograft panel, we selected three models, two of them harboring a homozygous deletion of CDKN2A/2B genes, and the last one a PBRM1 pathogenic variant (as control)." (PMID 36505864, 2022). "CDK4/6 inhibition appears as a promising strategy to manage advanced chordomas harboring a loss of CDKN2A/2B." (PMID 36505864, 2022). "Although CDKN2A mRNA would be expressed by non‐neoplastic cells in chordomas sample, this cannot be the case in the three chordoma cell lines in which mRNA was detected despite the loss of protein expression in the presence of monosomy for chromosome 9." (PMID 31916407, 2020). "A loss of CDKN2A in the chordoma cells was found as compared to the co-hybridized centromere 12 probe." (PMID 28515451, 2017). "Since CDKN2A gene loss is frequent in chordomas, the CDKN2A status was analysed by fluorescence in situ hybridization (FISH)." (PMID 28515451, 2017). "Accordingly, loss of expression of the CDKN2A protein in chordoma was also previously shown by immunostaining." (PMID 22613809, 2011). "Correspondingly, Hallor and co-workers observed loss of the CDKN2A locus with an incidence of 70% in chordoma, and with an even higher frequency considering just metastasizing lesions." (PMID 22613809, 2011).
chordoma (continued). "Tissue-based next-generation sequencing (NGS) was performed to evaluate for actionable mutations and returned only a cyclin-dependent kinase inhibitor 2A and 2B (CDKN2A/B) mutation, which is associated with cell cycle dysregulation but currently lacks a targeted therapeutic option in chordoma." (PMID 41404256, 2025). "CDKN2A, a cell cycle regulator, is commonly mutated in chordomas." (PMID 40323130, 2025). "Previous studies suggested that chordoma cells exhibiting a loss of CDKN2A (p16) may trigger universal activation of CDK4/6, implying the potential applicability of CDK4/6 inhibitor in chordoma treatment." (PMID 38369555, 2024). "C chordomas are characterized by higher chromosomal instability, according to results of copy number analysis and they have 9p deletion causing downregulation of cell cycle inhibitors CDKN2A/B." (PMID 37434245, 2023). "Notably, in our study 27% of chordomas with loss of p16 protein expression exhibited a normal diploid CDKN2A copy number status, a finding also reported by Le et al6 in two of 18 cases." (PMID 31916407, 2020). "Second, studies of genetic alterations in chordoma identified mutation or loss of the cell cycle regulator CDKN2A, which is of interest since we identified CDKN2C and CDKN3 as hits in a screen for proteins whose depletion enhances sensitivity to IGF-1R inhibition." (PMID 27200287, 2016). "Although the loss of CDKN2A and PTEN expressions is observed in various tumor types, it is thought to play a pivotal role in the pathogenesis of chordomas, with PTEN potentially serving as a prognostic and predictive biomarker." (PMID 39407739, 2024). "The main difference in CNAs between two chordoma clusters were chromosomic losses in chromosome 9 region, containing CDKN2A/B, affecting chordoma C cluster." (PMID 37434245, 2023). "RTK activation along with frequent loss of the cell cycle tumor suppressor CDKN2A in chordomas has motivated preclinical repurposing studies with CDK4/6 inhibitors and a Phase II trial involving palbociclib in CDKN2A-null chordoma patients (NCT03110744)." (PMID 36387127, 2022). "The CDKN2A/MTAP locus is frequently deleted in chordoma, suggesting an opportunity for repurposing PRMT5 or MAT2A inhibitors." (PMID 36387127, 2022). "Considering the frequency of genomic alterations affecting the CDKN2A/2B gene in chordomas, targeting this biomarker was fundamental." (PMID 36505864, 2022). "We first examined the two potential driver events, PBRM1 and CDKN2A/B status, in relation to chordoma-specific survival (CSS) and recurrence-free survival (RFS)." (PMID 33536423, 2021). "Consistent with findings from previous studies of sacral chordoma, we found that alterations of PBRM1 and CDKN2A/2B locus were the most common events in chordoma." (PMID 33536423, 2021). "Treatment of a CDKN2A-deleted chordoma cell line in vitro with palbociclib, for example, resulted in significant growth inhibition." (PMID 32733369, 2020). "Results from 274 of these samples were informative: the majority (167/274, 61%) of chordomas harboured CDKN2A copy number alterations, the most frequent event being copy number loss which was detected in 138/167 samples (83%)." (PMID 31916407, 2020). "Whole genome sequencing previously reported 5 revealed copy number alterations at the CDKN2A locus in 7 of 10 chordomas studied." (PMID 31916407, 2020). "The expression of p16/CDKN2A, the second most commonly inactivated tumour suppressor gene in cancer, is lost in the majority of chordomas." (PMID 31916407, 2020). "Much of the reported evidence available to date implies that this loss is associated with either a heterozygous or homozygous deletion of the region covering the CDKN2A locus but the number of chordoma samples studied using both markers is limited." (PMID 31916407, 2020).
chordoma (continued). "This prompted us to interrogate a large number of chordoma samples with the aim of increasing our understanding of the role of CDKN2A inactivation in the pathogenesis of chordoma." (PMID 31916407, 2020). "Cytogenetically, chordomas are characterized by deletion of the chromosome 9p21 locus containing the CDKN2A/2B genes (70% of cases), and gain of the chromosome 6q27 locus containing the T gene (brachyury) present in about half of the chordomas." (PMID 26888362, 2016). "Only one tested chordoma case (CH33) showeddefinitive evidence of CDKN2A promoter methylation withpositive PCR amplification products using both sets of methylation specificprimers." (PMID 21602918, 2011). "The loss of the latterputative genes, CDKN2A and CDKN2B, was identifiedin 70% of classical chordoma biopsies evaluated with bacterial artificialchromosome (BAC) array CGH." (PMID 21602918, 2011). "In the chordoma, PD3808a, the CDKN2A gene is homozygously deleted, with one of the copies probably lost through chromothripsis." (PMID 21215367, 2011). "Additionally, homozygous deletions of CDKN2A and CDKN2B genes, which are common in chordoma, suggest potential susceptibility to CDK4/6 inhibitors." (PMID 39941902, 2025). "CDKN2A copy number loss has been identified as the most frequent genomic alteration in chordomas, resulting in the absence of the p16INK4a protein, an inherent negative regulator of cyclin-dependent kinases 4 and 6 (CDK4/6)." (PMID 37046638, 2023). "In chordomas, the regulatory gene CDKN2A is also frequently lost, and thus, CDK4/6 may be in an over-activated state, although multiple upstream seem to be the input in the dysregulation of CDK4/6 activity." (PMID 36505864, 2022). "Homozygous deletion of the regulatory gene CDKN2A has been described as the most frequent genetic alteration in chordomas and may be considered as a potential theranostic marker." (PMID 36505864, 2022). "Additionally, the presence of a CCNE1 deletion was exclusively found in the group of chordoma patients with better outcome, whereas RB1 and CDKN2A/2B deletions were mainly found in the group of chordoma patients with worse outcome." (PMID 36439461, 2022). "In our chordoma PDX panel, homozygous loss of CDKN2A/2B was reported in 53.8% of the xenografts, followed by mutations affecting the SWI/SNF complexes (33.3%), representing most of genetic alterations found in chordomas." (PMID 35326637, 2022). "In this current study, we explored the antitumor effect of the targeted therapy palbociclib in three PDX chordoma models in order to consider the homozygous deletion of CDKN2A/2B as a theranostic biomarker of response to palbociclib, as suggested in other cancer types." (PMID 36505864, 2022). "Both homozygous and heterozygous copy number losses of CDKN2A have been identified in chordomas." (PMID 32733369, 2020). "Copy number gains/losses present in more than ≥50% of patients of well-known cancer associated genes for example CDKN2A, CDKN2B, RAF1 and PTEN were found and may play an important role in chordoma development." (PMID 23533570, 2013). "Importantly, the CDKN2A tumor suppressor gene, which maps to 9p21.3, is reported to be lost in a high percentage (60%) of chordomas." (PMID 22613809, 2011). "There would still be the need for additional mutations in cancer genes, exemplified by the second hits in CDKN2A seen in the chordoma and thyroid cancer samples, but we might anticipate the emergent tumor having shorter latency." (PMID 21215367, 2011). "Additionally, the presence of a CCNE1 deletion occurred exclusively in cluster 2 (8/10) chordomas and low-risk-group (6/10) chordomas, whereas all RB1 and CDKN2A/2B deletions occurred in cluster 1 and RB1 (5/6) deletions and CDKN2A/2B (2/3) deletions patients who were in the high-risk group." (PMID 36439461, 2022).
chordoma (continued). "We did not observe tumor response to palbociclib with the xenograft CD39 (p = 0.40) (which did not harbor a loss of CDKN2A/2B); such an observation raises the possibility to consider CDKN2A/2B loss as a theranostic marker of palbociclib antitumor efficacy in chordomas." (PMID 36505864, 2022). "Importantly, in chordoma the CDK4/6 regulatory gene CDKN2A (also known as p16) is frequently lost." (PMID 32737414, 2020). "In contrast, adult chordoma more commonly displays PBRM1 alterations and homozygous deletions of the CDKN2A/2B locus, reflecting the findings in this study." (PMID 39941902, 2025). "In summary, we identified candidate driver events (PBRM1+, SETD2+, CDKN2A/B+, TBXT/LYST+) in 33.75% (27 out of 80) of the skull-base chordoma patients we sequenced." (PMID 33536423, 2021). "The genetic alteration (deep deletion) frequency showed that 1/3rd of the chordoma samples have MTAP loss and CDKN2A, CDKN2B and CDKN2C loss; however, there is no loss in the folate pathway genes in the samples analyzed in personalized oncogenomics cBioPortal." (PMID 37147496, 2023). "It is otherwise difficult to explain how comparable levels of CDKN2A could be detected in chordomas with and without protein expression." (PMID 31916407, 2020). "However, the CDKN2A and CDKN2B loci in 9p21 were homo- or heterozygously lost in 70% of the tumours, a finding corroborated by fluorescence in situ hybridisation, suggesting that inactivation of these genes constitute an important step in chordoma development." (PMID 18071362, 2008). "In contrast, the other nine pediatric chordoma patients (diagnosed ≤ 20 years) appeared to have quiet genomes, characterized by low mutational burden and the absence of driver events (alterations in PBRM1, CDKN2A/B, TBXT genes), compared with adult chordoma patients." (PMID 33536423, 2021). "Taken together, our results are in agreement with a recent study in which immunohistochemic staining for the CDKN2A protein in chordoma consistently yielded negative results, and indicate that inactivation of CDKN2A may be important for chordoma development, although not tumour-type specific." (PMID 18071362, 2008).